SLC7A8 (solute carrier family 7 member 8)
Description:
Associates with SLC3A2 to form a functional heterodimeric complex that translocates small and large neutral amino acids with broad specificity and a stoichiometry of 1:1. Functions as amino acid antiporter mediating the influx of extracellular essential amino acids mainly in exchange with the efflux of highly concentrated intracellular amino acids. Has relatively symmetrical selectivities but strongly asymmetrical substrate affinities at both the intracellular and extracellular sides of the transporter. This asymmetry allows SLC7A8 to regulate intracellular amino acid pools (mM concentrations) by exchange with external amino acids (uM concentration range), equilibrating the relative concentrations of different amino acids across the plasma membrane instead of mediating their net uptake. May play an essential role in the reabsorption of neutral amino acids from the epithelial cells to the bloodstream in the kidney. Involved in the uptake of methylmercury (MeHg) when administered as the L-cysteine or D,L-homocysteine complexes, and hence plays a role in metal ion homeostasis and toxicity. Involved in the cellular activity of small molecular weight nitrosothiols, via the stereoselective transport of L-nitrosocysteine (L-CNSO) across the transmembrane. Imports the thyroid hormone diiodothyronine (T2) and to a smaller extent triiodothyronine (T3) but not rT 3 or thyroxine (T4). Mediates the uptake of L-DOPA (By similarity). May participate in auditory function (By similarity). Mediates the uptake of leucine and 3-iodo-L-tyrosine (MIT). Mediates the uptake of 3,5-diiodo-L-tyrosine (DIT).
Synonyms: LAT2; LPI-PC1
Tractability: Small molecule: a structure with a bound ligand is known. Antibody: UniProt places it where antibodies can reach, with high confidence; its Gene Ontology location is reachable by antibodies, with high confidence; UniProt predicts a signal peptide or a membrane-spanning region. PROTAC: ubiquitination databases record sites on it; its protein half-life has been measured.
Target class: Transporter; SLC07 Cationic amino acid transporter/glycoprotein-associated family; Electrochemical transporter; SLC03 and SLC07 families of heteromeric amino acid transporters (HATs); SLC superfamily of solute carriers
Gene: Protein-coding gene on chromosome 14 (23,125,295 to 23,183,674, reverse strand). Ensembl gene ENSG00000092068.
Subcellular location: Cell membrane; Basolateral cell membrane
Pathways (Reactome):
Hemostasis: Basigin interactions
Transport of small molecules: Amino acid transport across the plasma membrane
Gene Ontology:
Molecular function: amino acid transmembrane transporter activity; antiporter activity; L-alanine transmembrane transporter activity; L-leucine transmembrane transporter activity; neutral L-amino acid transmembrane transporter activity; protein binding; protein heterodimerization activity; thyroid hormone transmembrane transporter activity; toxin transmembrane transporter activity; transmembrane transporter activity; glycine transmembrane transporter activity; L-amino acid transmembrane transporter activity; peptide antigen binding
Biological process: amino acid import across plasma membrane; amino acid transport; L-alanine import across plasma membrane; L-leucine import across plasma membrane; neutral amino acid transport; thyroid hormone transport; amino acid transmembrane transport; glycine transport; L-leucine transport; proline transmembrane transport; transport across blood-brain barrier; tryptophan transport; valine transport; transmembrane transport
Cellular component: basal plasma membrane; basolateral plasma membrane; microvillus membrane; plasma membrane; transmembrane transporter complex; apical plasma membrane; membrane
Genetic constraint (gnomAD): Loss-of-function variants: 33 observed, 55.65 expected, observed/expected ratio (o/e) 0.59, 90% interval 0.45 to 0.79. The upper end of that interval is the gene's LOEUF score, 0.79, which puts it in group 3 of 6, group 1 being the genes least tolerant of losing a copy. Missense variants: 612 observed, 707.3 expected, observed/expected ratio (o/e) 0.87, 90% interval 0.81 to 0.93. Synonymous variants: 257 observed, 290.24 expected, observed/expected ratio (o/e) 0.89, 90% interval 0.8 to 0.98.
Homologues: Orthologues: chimpanzee SLC7A8 (100% identical), macaque SLC7A8 (99% identical), rabbit SLC7A8 (93% identical), dog SLC7A8 (93% identical), guinea pig SLC7A8 (92% identical), rat Slc7a8 (92% identical), mouse Slc7a8 (91% identical), pig SLC7A8 (90% identical), tropical clawed frog slc7a8 (79% identical), zebrafish slc7a8a (79% identical), zebrafish slc7a8b (72% identical), Drosophila melanogaster CG1607 (44% identical), and 10 more. Paralogues in human: SLC7A10 (62% identical), SLC7A5 (50% identical), SLC7A6 (44% identical), SLC7A7 (44% identical), SLC7A11 (40% identical), SLC7A9 (39% identical), SLC7A13 (27% identical), SLC7A3 (24% identical), SLC7A1 (24% identical), SLC7A4 (24% identical), SLC7A2 (23% identical), SLC7A14 (21% identical).
Diseases named in the same sentence as SLC7A8 in open-access papers:
SLC7A8 is named in the same sentence as 52 diseases in open-access papers, as found by Europe PMC text mining. Sharing a sentence is not in itself a finding about the gene and the disease. The quoted sentences say what the papers report.
breast carcinoma (8 papers, 2018 to 2024). "Similar associations of SLC7A8 mRNA with the molecular subtypes were seen using Breast Cancer Gene-Expression Miner." (PMID 32200487, 2020). "Among the cationic amino acid transporter/glycoprotein-associated family, SLC7A5, SLC7A7, and SLC7A8 are highly expressed in luminal subtypes of breast cancer, as well as SLC7A9 and SLC7A10, the activity of which is observed exclusively in the case of positive HER2 expression." (PMID 39852119, 2024). "Several studies have shown the dependence of this receptor on the positive expression of HR and HER2, which suggests a specific expression of SLC7A8 in the luminal B subtype of breast cancer." (PMID 39852119, 2024). "SLC7A8 was highly expressed in estrogen receptor (ER)-positive breast cancer and was a marker of good prognosis in these patients." (PMID 38244585, 2024). "In multivariate analysis, SLC7A8 mRNA and SLC7A8 protein were independent factors for longer breast cancer specific survival (P = 0.01 and P = 0.03), respectively." (PMID 32200487, 2020). "The relationship between high SLC7A8 mRNA expression and good patient outcome was verified using Breast Cancer Gene-Expression Miner." (PMID 32200487, 2020). "In breast cancer, SLC7A8 mRNA expression was elevated in samples from estrogen receptor alpha-positive breast cancer patients." (PMID 30419950, 2018). "SLC7A8 was shown to be a good prognostic marker for breast cancer." (PMID 38244585, 2024). "SLC1A5 plays a role in lung cancer and SLC7A8 is involved in breast cancer development." (PMID 35565312, 2022). "Human breast cancer cells, including MCF-7, were shown to express LAT1 (SLC7A5) and LAT2 (SLC7A8); however, only SLC6A14 requires chloride ions for its activity." (PMID 34359969, 2021).
pancreatic cancer (7 papers, 2019 to 2024). "The solute carrier SLC7A8 is known to promote glycolysis and chemoresistance in pancreatic cancer in an mTOR-dependent manner." (PMID 32785098, 2020). "SLC7A8 or LAT-2 is an L-type amino acid transporter-2 protein that binds and regulates mechanistic target of rapamycin kinase (mTOR) activation in pancreatic cancer." (PMID 32235589, 2020). "In addition, SLC7A8 was found to increase gemcitabine resistance in pancreatic cancer." (PMID 38705513, 2024). "However, another study showed that SLC7A8 regulates two glutamine-dependent positive feedback loops for activation of the mTOR pathway including LAT2/p-mTORSer2448 and glutamine/p-mTORSer2448/glutamine synthetase loop to enhance glycolysis in pancreatic cancer." (PMID 38705513, 2024).
breast tumors (5 papers, 2014 to 2025). "High PRODH, ALDH18A1, and ALDH4A1 were expressed in breast tumours with high SLC7A8 expression (all P ≤ 0.004)." (PMID 32200487, 2020). "Apart from SLC7A8, all the following amino acid transporters, SLC7A5, SLC3A2, SLC7A11 and SLC38A2, were significantly expressed in breast tumours with high SLC1A5 expression (P < 0.01)." (PMID 39843491, 2025). "However, this only has been validated at the mRNA level in a subset of breast tumours and melanoma cell lines, which showed however more than five times increase in SLC7A5 expression compared to SLC7A8." (PMID 32200487, 2020). "Only 2 proteins, MLPH and SLC7A8, displayed low frequencies of positivity in non-apocrine breast tumor subtypes (2,9% and 9,7% respectively)." (PMID 25389781, 2014).
age-related hearing loss (4 papers, 2018 to 2025). "LAT2 deficiency, caused by mutations or deletion of the SLC7A8 gene encoding the L-type amino acid transporter 2, has also been linked to age-related hearing loss (ARHL) through its critical role in amino acid transport in the inner ear." (PMID 41142409, 2025). "SLC7A8 plays a role in age-related hearing loss and regulates adipose tissue biology and lipid accumulation, both aspects closely related to MDPL syndrome." (PMID 41083899, 2025). "Functional studies of human SLC7A8 variants (14:23597290A/T, 14:23598917G/A, 14:23608641C/T, 14:23598870G/A) found in age-related hearing loss (ARHL) patients showed decreased LAT2 transport activity, further supporting the causative link." (PMID 41142409, 2025). "Slc7a8 has also been demonstrated to be a novel gene involved in age-related hearing loss, as suppression of this gene causes damage to the Corti apparatus, spiral ganglia, and vascular striae." (PMID 36139057, 2022). "The present work provides evidence that the amino acid transporter SLC7A8/SLC3A2 has a direct role in age-related hearing-loss (ARHL)." (PMID 29355479, 2018). "The experiments suggest that certain mutations in the gene for SLC7A8 are likely an inherited cause of age-related hearing loss." (PMID 29355479, 2018). "Finally, we investigated SLC7A8, a neutral amino acid transmembrane transporter involved in age-related hearing loss." (PMID 41083899, 2025).
melanoma (4 papers, 2019 to 2022). A malignant, usually aggressive tumor composed of atypical, neoplastic melanocytes. "Data from Oncomine revealed a significant upregulation of SLC7A8 in several cancers, including breast, colorectal, head and neck, leukaemia, lymphoma, and melanoma." (PMID 32200487, 2020). "Carrier-mediated proteins overexpressed in melanoma cells include L-type amino acid transporter 1 (LAT1/SLC7A5), L-type amino acid transporter 2 (LAT2/SLC7A8), alanine-serine-cysteine transporter 2 (ASCT2/SLC1A5), and glucose uptake transporter 1 (GLUT1)." (PMID 31717859, 2019).
Obesity (4 papers, 2022 to 2025). Accumulation of substantial excess body fat. "Furthermore, our histological findings revealed that the negative effects of DIO on different organs and tissues are improved with slc7a8 deletion, suggesting that this gene may contribute to the development of some obesity-associated comorbidities." (PMID 35205177, 2022). "Hence, SLC7A8 could serve as a potential therapeutic target to combat the development of obesity and other pathophysiological conditions associated with excess lipid accumulation." (PMID 35205177, 2022). "SLC7A8 (LAT2) facilitates amino acid transport and its deficiency prevents diet-induced obesity, reduces glucose intolerance, limits lipid accumulation in multiple organs, and diminishes macrophage infiltration." (PMID 41458991, 2025). "This study investigated the role of a previously identified novel human adipogenic gene, SLC7A8, in diet-induced obesity and its effect on adipose tissue accumulation in different organs and tissues." (PMID 35205177, 2022). "This study demonstrates that targeting slc7a8 protects against diet-induced obesity by reducing lipid accumulation in multiple organs and suggests that if targeted, has the potential to mitigate the development of obesity-associated comorbidities." (PMID 35205177, 2022). "The current study has investigated the role of SLC7A8 in adipose tissue biology using a mouse model of diet-induced obesity." (PMID 35205177, 2022). "Here, we report findings from targeting a novel potential human adipogenic gene (SLC7A8) under conditions of obesity development using a mouse model of diet-induced obesity (DIO)." (PMID 35205177, 2022). "Overall, the results from this study show that slc7a8 is an important molecular regulator of obesity development and mediates its function by reducing lipid accumulation in multiple organs." (PMID 35205177, 2022). "Similarly, deletion of SLC7A8 in mice offers significant protection against diet-induced obesity and enhances glucose metabolism." (PMID 38918843, 2024). "This suggests that slc7a8 deletion was protective against diet-induced obesity." (PMID 35205177, 2022). "We observed that the deletion of slc7a8 attenuated adipose tissue accumulation in DIO; this could mitigate the development of obesity-associated lung pathologies." (PMID 35205177, 2022). "Overall, the results from this study suggest that slc7a8 might be a potential therapeutic target for controlling DIO, as well as for mitigating the development of some of the pathophysiological conditions associated with obesity." (PMID 35205177, 2022). "This study has demonstrated that deletion of slc7a8 in mice is protective against DIO by significantly reducing adipose tissue mass and lipid accumulation in multiple organs and tissues, and results in improved glucose tolerance in diet-induced obesity." (PMID 35205177, 2022).
Age-related cataract (3 papers, 2019 to 2025). A type of cataract (opacification of the lens) that forms during the course of aging. "SLC7A8, recognized as a transporter protein, displayed heightened expression in lens epithelial cells and is associated with congenital or age-related cataracts." (PMID 40837408, 2025). "Screening SLC7A8 in patients diagnosed with congenital or age-related cataract yielded one homozygous single nucleotide deletion segregating in a family with congenital cataract." (PMID 31231240, 2019).
cataract (3 papers, 2019 to 2025). Partial or complete opacity of the crystalline lens of one or both eyes that decreases visual acuity and eventually results in blindness. "Loss of the amino acid transporter LAT2 (Slc7a8) causes a strong imbalance in lens amino acid concentrations and is associated with cataracts in both mouse and humans." (PMID 32833997, 2020).
lymphoma (3 papers, 2020 to 2023). A malignant (clonal) proliferation of B- lymphocytes or T- lymphocytes which involves the lymph nodes, bone marrow and/or extranodal sites. "In addition, the expression of AhR, CYP1A1, CYP1B1, RUNX1 and SLC7A8 was upregulated in MEPs of individuals with lymphoma, concomitant with enhanced nuclear localization of AhR." (PMID 37919525, 2023).
ovarian carcinoma (3 papers, 2018 to 2021). A malignant neoplasm originating from the surface ovarian epithelium. "A total of 10 overlapped genes (SLC7A7, SLC7A8, COL4A5, etc.)and one metabolite (L-threonine) were significantly correlated with the pathway of protein digestion and absorption in ovarian cancer." (PMID 34539736, 2021). "Meanwhile, another study showed that the expression of the SLC7A8 gene was significantly decreased in the paclitaxel-resistant W1 human ovarian cancer cell line compared with W1 parental cells; thus, SLC7A8 might be involved in reversing drug resistance in ovarian cancer." (PMID 30419950, 2018).
Uterine leiomyoma (3 papers, 2020 to 2025). The presence of a leiomyoma of the uterus. "Another study also revealed that progesterone significantly upregulates SLC7A8 mRNA and SLC7A8 protein expressions, in uterine leiomyoma tissues, and knockdown of SLC7A8 markedly increased leiomyoma cell proliferation." (PMID 32200487, 2020). "Knockdown of SLC7A8 enhanced the proliferation of uterine leiomyoma cells." (PMID 38244585, 2024). "In uterine leiomyoma tissues, luteinizing hormone upregulated SLC7A8." (PMID 38244585, 2024).
autism spectrum disorder (2 papers, 2019 to 2022). A spectrum of developmental disorders that includes autism, and Asperger syndrome. "Moreover, the research found that in Chd8+/− mice model of autism spectrum disorder (ASD), increased expression of neutral amino acid transporters Slc6a19, Slc7a8, and Slc7a15 resulted in increased serum glutamine and tryptophan levels." (PMID 36620044, 2022).
hearing loss (2 papers, 2018 to 2025). "Mutations in the gene for SLC7A8 that partially block the door and prevent the flow of amino acids were found in people with hearing loss." (PMID 29355479, 2018). "DMGs for which gene variants were identified in association with hearing loss were also identified, including COL9A3 and SLC7A8; CACHD1 was also identified in connection to hearing loss in mice." (PMID 41159936, 2025). "Altogether, the data presented suggests that the absence of SLC7A8 in fibrocytes might contribute a metabolic component to the progression of hearing loss." (PMID 29355479, 2018).
allergic asthma (1 paper, 2025). A asthma with a basis in a pathological type I hypersensitivity reaction. "We noted that SLC7A5 (LAT1), SLC7A8 (LAT2), and SLC3A2 (CD98), part of LAT1 and LAT2 heterodimer complexes, were significantly downregulated in allergic asthma but not in allergic rhinitis, suggesting decreased transport of Phe into the Th2 cells in more advanced allergic disease." (PMID 41308641, 2025).
Aminoaciduria (1 paper, 2025). An increased concentration of an amino acid in the urine. "Mutations or dysfunctions in the SLC7A8 gene encoding LAT2 can impair the transporter's function, leading to aminoacidurias characterized by the abnormal excretion of amino acids in urine." (PMID 41142409, 2025).
apocrine carcinoma (1 paper, 2014). "It is not inconceivable that MLPH and SLC7A8 proteins are expressed and function in apocrine carcinoma at a very low level but, consequently, all oscillations in their expression are below the resolving power of the IHC." (PMID 25389781, 2014).
atherosclerosis (1 paper, 2025). A disease characterized by the build-up of fatty material and calcium deposition in the arterial wall resulting in partial or complete occlusion of the arterial lumen. "In addition, leucine and isoleucine transported by SLC7A8 are important for maintaining normal metabolic functions of immune cells and regulating cellular activation through pathways, such as mTOR, thereby influencing the progression of cardiovascular diseases, including atherosclerosis." (PMID 40727388, 2025).
cholangiocarcinoma (1 paper, 2024). A carcinoma that arises from the intrahepatic biliary tree (intrahepatic cholangiocarcinoma) or from the junction, or adjacent to the junction, of the right and left hepatic ducts (hilar cholangiocarcinoma). "Furthermore, the results of increased gemcitabine sensitivity and decreased cell growth after knockdown by siSLC7A8 support the involvement of the SLC7A8 in chemoresistance in cholangiocarcinoma." (PMID 38992159, 2024).
colon cancer (1 paper, 2020). "In addition, SLC7A8 was upregulated alongside two tumour suppressor genes, CEACAM1 and BMP2, in human colon cancer cells after exposure to anti-tumour agent." (PMID 32200487, 2020).
deafness (1 paper, 2018). An inherited or acquired condition characterized by the complete loss of the ability to hear from one or both ears. "The ablation of SLC7A8 in a mouse model causes deafness with ARHL characteristics, defective audition at high-frequencies with early onset in homozygotes and progressive worsening in heterozygotes with age." (PMID 29355479, 2018).